ESRRB (estrogen related receptor beta)
Description:
[Isoform 3]: Transcription factor that binds a canonical ESRRB recognition (ERRE) sequence 5'TCAAGGTCA-3' localized on promoter and enhancer of targets genes regulating their expression or their transcription activity. Plays a role, in a LIF-independent manner, in maintainance of self-renewal and pluripotency of embryonic and trophoblast stem cells through different signaling pathways including FGF signaling pathway and Wnt signaling pathways. Involved in morula development (2-16 cells embryos) by acting as a regulator at the 8-cell stage (By similarity). Upon FGF signaling pathway activation, interacts with KDM1A by directly binding to enhancer site of ELF5 and EOMES and activating their transcription leading to self-renewal of trophoblast stem cells. Also regulates expression of multiple rod-specific genes and is required for survival of this cell type (By similarity). Plays a role as transcription factor activator of GATA6, NR0B1, POU5F1 and PERM1. Plays a role as transcription factor repressor of NFE2L2 transcriptional activity and ESR1 transcriptional activity. During mitosis remains bound to a subset of interphase target genes, including pluripotency regulators, through the canonical ESRRB recognition (ERRE) sequence, leading to their transcriptional activation in early G1 phase. Can coassemble on structured DNA elements with other transcription factors like SOX2, POU5F1, KDM1A and NCOA3 to trigger ESRRB-dependent gene activation. This mechanism, in the case of SOX2 corecruitment prevents the embryonic stem cells (ESCs) to epiblast stem cells (EpiSC) transition through positive regulation of NR0B1 that inhibits the EpiSC transcriptional program. Also plays a role inner ear development by controlling expression of ion channels and transporters and in early placentation (By similarity). [Isoform 1]: Transcription factor that binds a canonical ESRRB recognition (ERRE) sequence 5'TCAAGGTCA-3' localized on promoter and enhancer of targets genes regulating their expression or their transcription activity. Positively regulates ESR1 transcriptional activity upon E2 stimulation.
Synonyms: ESRL2; NR3B2; ERR2; ERRbeta; ERRb; DFNB35; ERR beta-2; ERRbeta2
Tractability: Small molecule: a structure with a bound ligand is known; a high-quality ligand is known; it belongs to a druggable protein family. PROTAC: ubiquitination databases record sites on it; its protein half-life has been measured; a small molecule that binds it is known.
Target class: Transcription factor; Nuclear hormone receptor subfamily 3 group B member 2; Nuclear receptor; Nuclear hormone receptor subfamily 3; Nuclear hormone receptor subfamily 3 group B
Gene: Protein-coding gene on chromosome 14 (76,310,712 to 76,501,837, forward strand). Ensembl gene ENSG00000119715.
Subcellular location: Nucleus; Cytoplasm; Chromosome
Subcellular location (Human Protein Atlas): Nucleoplasm; Cytosol
Pathways (Reactome):
Gene expression (Transcription): Nuclear Receptor transcription pathway
Gene Ontology:
Molecular function: sequence-specific DNA binding; sequence-specific double-stranded DNA binding; cis-regulatory region sequence-specific DNA binding; DNA-binding transcription activator activity, RNA polymerase II-specific; DNA-binding transcription factor activity; DNA-binding transcription factor activity, RNA polymerase II-specific; estrogen response element binding; nuclear receptor activity; RNA polymerase II cis-regulatory region sequence-specific DNA binding; RNA polymerase II complex binding; RNA polymerase II-specific DNA-binding transcription factor binding; DNA binding; nuclear steroid receptor activity; steroid binding; zinc ion binding
Biological process: regulation of DNA-templated transcription; stem cell population maintenance; cell dedifferentiation; embryonic placenta development; inner ear development; morula formation; negative regulation of stem cell differentiation; photoreceptor cell maintenance; positive regulation of DNA-templated transcription; positive regulation of stem cell population maintenance; positive regulation of transcription by RNA polymerase II; regulation of stem cell division; regulation of transcription by RNA polymerase II; somatic stem cell population maintenance; stem cell division; intracellular receptor signaling pathway; nuclear receptor-mediated steroid hormone signaling pathway
Cellular component: nucleoplasm; nucleus; chromatin; chromosome; condensed chromosome; cytoplasm; integrator complex
Genetic constraint (gnomAD): Loss-of-function variants: 16 observed, 43.41 expected, observed/expected ratio (o/e) 0.37, 90% interval 0.25 to 0.56. The upper end of that interval is the gene's LOEUF score, 0.56, which puts it in group 2 of 6, group 1 being the genes least tolerant of losing a copy. Missense variants: 487 observed, 607.92 expected, observed/expected ratio (o/e) 0.8, 90% interval 0.74 to 0.86. Synonymous variants: 246 observed, 260.41 expected, observed/expected ratio (o/e) 0.94, 90% interval 0.85 to 1.05.
Gene-disease validity (ClinGen):
ClinGen rates the evidence that ESRRB causes each of these diseases.
nonsyndromic genetic hearing loss (autosomal recessive): Definitive. A disease characterized by hearing loss that is not part of a larger syndrome.
Homologues: Orthologues: pig ESRRB (98% identical), dog ESRRB (98% identical), guinea pig ESRRB (98% identical), rabbit ESRRB (98% identical), macaque ESRRB (96% identical), chimpanzee ESRRB (95% identical), mouse Esrrb (93% identical), rat Esrrb (93% identical), zebrafish esrrb (77% identical), tropical clawed frog esrrb (67% identical), Drosophila melanogaster ERR (43% identical). Paralogues in human: ESRRG (77% identical), ESRRA (56% identical), ESR1 (34% identical), ESR2 (33% identical), NR3C2 (27% identical), PGR (26% identical), NR3C1 (26% identical), AR (25% identical).